INS (insulin)
Diseases named in the same sentence as INS in open-access papers (continued):
Sharing a sentence is not in itself a finding about the gene and the disease.
hyperinsulinemic hypoglycemia (continued). "Another critical yet underrecognized complication is postprandial hyperinsulinemic hypoglycemia (PHH), particularly in patients with pre-existing T2DM, caused by exaggerated insulin responses from elevated GLP-1 levels." (PMID 40698210, 2025). "Postprandial insulin hypersecretion can result in hyperinsulinemic hypoglycemia, with impaired counter-regulatory hormone responses." (PMID 39981480, 2025). "Given the role of lipoic acid in regulating insulin secretion, the involvement of impaired mitochondrial lipoic acid biosynthesis in the clinical presentation of hyperinsulinemic hypoglycemia cannot be excluded." (PMID 41030468, 2025). "When his intravenous glucose level was 2.0 mmol/l, his insulin level was up to 5.5 μIU/ml, and his C-peptide level was 0.46 nmol/l, which indicated hyperinsulinemic hypoglycemia." (PMID 38373926, 2024). "This excessive secretion of insulin by the pancreas in reaction to the incretins is a significant contributor to postprandial hyperinsulinemic hypoglycemia." (PMID 39555226, 2024). "Hojlund and colleagues also propose decreased insulin degradation as a mechanism of hyperinsulinemic hypoglycemia." (PMID 39483531, 2024). "The exaggerated incretin response, especially GLP-1, leads to an inappropriate and excessive stimulation of insulin secretion, resulting in postprandial hyperinsulinemic hypoglycemia." (PMID 39555226, 2024). "Critical blood samples showed inappropriate insulin levels while hypoglycemic and hypoketonemic, consistent with a diagnosis of hyperinsulinemic hypoglycemia." (PMID 35721755, 2022). "Newly established criteria of insulin, C-peptide, and proinsulin for the diagnosis of endogenous hyperinsulinemic hypoglycemia were derived by ROC analysis in our cohort." (PMID 36339408, 2022). "Assessment of insulin secretion is key to diagnose postprandial hyperinsulinemic hypoglycemia (PHH), an increasingly recognized complication following bariatric surgery." (PMID 33790855, 2021). "While the underlying mechanisms remain to be fully elucidated, excessive postprandial insulin exposure due to exaggerated insulin secretion and/or diminished insulin clearance are key pathophysiological hallmarks of postprandial hyperinsulinemic hypoglycemia." (PMID 33790855, 2021). "The spectrum of disorders associated with hyperinsulinemic hypoglycemia (HHI) has vastly increased over the past 20 years with identification of molecular, metabolic and cellular pathways involved in the regulation of insulin secretion and its actions." (PMID 33910593, 2021). "Determination of C-peptide is important in the investigation of unexplained hyperinsulinemic hypoglycemia because a high C-peptide concentration usually indicates endogenous insulin hypersecretion." (PMID 34051096, 2021). "Hyperinsulinemic hypoglycemia (HH) is characterized by unregulated insulin release, leading to persistently low blood glucose concentrations with lack of alternative fuels, which increases the risk of neurological damage in these patients." (PMID 32185602, 2020). "Eleven patients had documented blood glucose, insulin, and C-peptide levels, which were all consistent with the criteria for endogenous hyperinsulinemic hypoglycemia." (PMID 30522468, 2018). "IAS should be considered in patients with hyperinsulinemic hypoglycemia and a high insulin/C-peptide ratio." (PMID 30085133, 2018). "Six patients with hyperinsulinemic hypoglycemia and detectable circulating anti–insulin antibody (IA)." (PMID 30085133, 2018). "Insulin autoimmune syndrome (IAS) features hyperinsulinemic hypoglycemia due to insulin autoantibodies in exogenous insulin-naive individuals." (PMID 30085133, 2018). "Hyperinsulinemic hypoglycemia (HH) is biochemically characterized by the unregulated secretion of insulin from the pancreatic β-cells in the presence of low blood glucose levels." (PMID 27065949, 2016).
hyperinsulinemic hypoglycemia (continued). "Hyperinsulinemic hypoglycemia is characterized by the dysregulation of insulin secretion from pancreatic β-cells." (PMID 27065949, 2016). "The pathogenesis of transient hyperinsulinemic hypoglycemia in SGA infants is poorly understood but may be related in part to suppression of fetal insulin secretion by premature induction of cortisol and/or catecholamines." (PMID 37529595, 2023). "Following initial laboratory workup suggestive of endogenous hyperinsulinemic hypoglycemia, the results of a serum oral hypoglycemic panel confirmed the presence of glipizide, an unprescribed insulin secretagogue of the sulfonylurea class, in the patient's serum." (PMID 35898373, 2022). "Late dumping syndrome, NIPHS and nesidioblastosis could have the same physiopathology with hyperfunction of beta cells causing hyperinsulinemic hypoglycemia, although different mechanisms, including GLP-1 and post-prandial insulin surge, may be involved." (PMID 35716625, 2022). "At the age of eight years, a glucose tolerance test was performed, showing reactive hyperinsulinemic hypoglycemia 2 h after oral administration of 1.75 g glucose/kg body weight (plasma glucose 46 mg/dL [2.55 mmol/L], insulin 10.3 mU/L, BHB 0.1 mmol/L, free fatty acids [FFA] 1.0 mmol/L)." (PMID 35897673, 2022). "An end-of-fast insulin level ≥ 3 μIU/ml, C-peptide level ≥ 0.6 ng/ml, and proinsulin level ≥ 5 pmol/l with end-of-fast glucose level ≤ 3.0 mmol/l have been established as the criteria for endogenous hyperinsulinemic hypoglycemia." (PMID 36339408, 2022). "In the future, ablating insulin-producing cells using rtPDT with exendin-4-IRDye700DX might provide a new, minimally invasive treatment method for patients with hyperinsulinemic hypoglycemia." (PMID 32385165, 2020). "Insulin autoimmune syndrome is a rare cause of hyperinsulinemic hypoglycemia characterized by autoantibodies to human insulin without previous insulin use." (PMID 30853027, 2019). "Insulin autoimmune syndrome (IAS) is a rare cause of hyperinsulinemic hypoglycemia characterized by high titers of autoantibodies to human insulin in individuals without previous insulin use." (PMID 30853027, 2019). "With a blood glucose of 2.5 mmol/L and an inadequately high insulin level of 37 μE/mL, the diagnosis of hyperinsulinemic hypoglycemia of unknown etiology was made and therapy with sandostatin was initiated without achieving stabilization of blood glucose levels." (PMID 40705962, 2026). "Thus, whereas islet cells derived from patients with persistent hyperinsulinemic hypoglycemia of infancy lose their hormone expression under 1 g culture conditions, they reactivate their insulin expression when grown in simulated μg produced through high-aspect-ratio vessel technology." (PMID 39329769, 2024). "Since inaccuracy in C-peptide kinetics may negatively affect the estimation of insulin secretion, the applicability of the Van Cauter population model to predict C-peptide kinetics in patients suffering from postprandial hyperinsulinemic hypoglycemia must be investigated." (PMID 33790855, 2021). "Insulin autoimmune syndrome (IAS), also known as Hirata syndrome, is a rare cause of spontaneous hyperinsulinemic hypoglycemia, most commonly reported in Asian populations, characterized by the presence of insulin autoantibodies in individuals without prior exposure to exogenous insulin." (PMID 42291946, 2026). "Despite the pattern of hyperinsulinemic hypoglycemia and low C-peptide, he was diagnosed with IAS based on the presence of insulin autoantibodies." (PMID 39119412, 2024). "First, the patient presented with diabetes (most likely due to the predominance of the glucagonoma) and later developed hyperinsulinemic hypoglycemia, which is probably the consequence of the GLP-1 excess, which acts as a potent insulin secretagogue." (PMID 37371827, 2023).
hyperinsulinemic hypoglycemia (continued). "Recently, the human glucose-responsive insulin secreting NES2Y cell line, derived from a patient with persistent hyperinsulinemic hypoglycemia of infancy, was established." (PMID 19545371, 2009). "A case of autoimmune insulin syndrome, characterized by elevated anti-insulin antibodies and hyperinsulinemic hypoglycemia, was reported following omeprazole administration in the absence of exogenous insulin use." (PMID 41440753, 2025). "While laboratory testing for insulin, C-peptide, and sulfonylurea levels was not completed in the ED, the clinical scenario strongly suggested endogenous hyperinsulinemic hypoglycemia." (PMID 40757084, 2025). "Insulin autoimmune syndrome (IAS) is characterized by spontaneous hyperinsulinemic hypoglycemia and the presence of insulin autoantibodies in high titers without exogenous insulin use." (PMID 39119412, 2024). "It is characterized by hyperinsulinemic hypoglycemia, elevated insulin autoantibody (IAA) titers, no prior exposure to exogenous insulin, and no pathological abnormalities of pancreatic islets." (PMID 39119412, 2024). "The dogs in this study had their serum insulin and glucose concentrations measured at the beginning and the end of the 96 h study periods, and none of the dogs had results that were suggestive of hyperinsulinemic hypoglycemia." (PMID 34941910, 2021). "Insulin autoimmune syndrome (IAS, or Hirata disease) denotes spontaneous hyperinsulinemic hypoglycemia due to insulin-binding autoantibodies in individuals not receiving insulin therapy." (PMID 34051096, 2021). "In patients presenting with hyperinsulinemic hypoglycemia with a nonpancreatic neuroendocrine tumor, the diagnosis of an ectopic insulin-secreting tumor should be considered, and investigated further with confirmatory insulin staining." (PMID 33505694, 2020). "Critical sampling demonstrated inappropriately detectable insulin and C-peptide, absent ketonuria, suppressed β-hydroxybutyrate, and a diagnostically significant glycemic response to glucagon, confirming hyperinsulinemic hypoglycemia (HH) consistent with congenital hyperinsulinism (CHI)." (PMID 42220696, 2026). "However, the patient's hypoglycemia did not respond well to medical treatment; the diagnosis of hyperinsulinemic hypoglycemia was made due to the presence of inappropriately high levels of insulin, proinsulin, and C-peptide during an episode of hypoglycemia." (PMID 30895162, 2019).
fibrosis (72 papers, 2007 to 2026). the formation of excess fibrous connective tissue in an organ or tissue in a reparative or reactive process. "It is apparent though that not all persons with diabetes have the same risk of hepatic steatosis and fibrosis, and this is modulated by insulin resistance." (PMID 38398781, 2024). "Twelve weeks after OAGB surgery, patients with a high risk of fibrosis showed larger reductions in body mass, systolic BP, serum insulin concentration, and HbA1c than those with a lower risk." (PMID 39339810, 2024). "In brief, regular aerobic exercise presents significant improvements in cardiac function and remodeling, improved glucose and insulin metabolism, and decreases cardiac fibrosis, apoptosis, and oxidative stress, thereby reducing the risk factors for cardiovascular disease." (PMID 35711309, 2022). "Fibrosis regression was associated with lower baseline insulin level (20 vs 33 μU/mL; P = .02) and decrease in all NAS components (steatosis grade −0.8 [0.1] vs −0.3 [0.9]; P < .001; lobular inflammation −0.5 [0.8] vs −0.2 [0.9]; P < .001; ballooning −0.7 [1.1] vs −0.1 [0.9]; P < .001)." (PMID 31584681, 2019). "Finally, advanced fibrosis was independently associated with fasting insulin, and with a high percentage of palmitic acid in RBC, in a binary logistic regression." (PMID 30380656, 2018). "In this study, we report for the first time that repeated administration of serum EVs from young mice to aged mice improved aged‐related fibrosis, increased locomotion, and whole‐body insulin sensitivity by increasing p‐Akt levels in the skeletal muscle." (PMID 39269881, 2024). "Metabolic dysfunction-associated steatotic liver disease (MASLD) is a multifactorial condition characterized by insulin resistance, oxidative stress, chronic low-grade inflammation, and sometimes fibrosis." (PMID 38140312, 2023). "Ectopic fat deposition and excessive lipid droplets (LDs) in the cytoplasm of cells promote impaired glucose-stimulated insulin secretion, reduce insulin storage, inhibit pro-insulin synthesis, increase pancreatic fibrosis, and accelerate islet cell apoptosis." (PMID 35845956, 2022). "A significant reduction in fasting blood glucose and insulin levels was observed and consequently a significant improvement in IR levels both in the group with mild to moderate fibrosis (F0–F2) and in those with advanced fibrosis (F3–F4)." (PMID 32782961, 2020). "Those with fibrosis regression had lower mean baseline fasting insulin levels (mean [SD], 20 vs 33 μU/mL; P = .02) and a greater decrease in AST and ALT levels from the time of the first to last biopsy (eTable 5 in the Supplement)." (PMID 31584681, 2019). "In the fibrosis study, both glucose and insulin levels were significantly reduced following I-BET151 treatment relative to the vehicle." (PMID 30467325, 2018). "In the present report, 6 mm full thickness skin wounds healed by granulation tissue formation resulting in fibrosis still present after 28 days, both in insulin treated and control wounds." (PMID 28587643, 2017). "The insulin secretion in the mild fibrosis group (F0 and F1) decreased relatively early with the decrease in blood glucose levels." (PMID 24223115, 2013). "This distinct fat distribution and the differential impact on insulin sensitivity might further affect the risk of NAFLD and subsequent fibrosis in male patients with T2DM." (PMID 39698035, 2024). "The independent remaining predictors of NAFLD-fibrosis were HbA1c, insulin and triglycerides." (PMID 33429859, 2021). "Japanese patients with NAFLD have significant fibrosis with reduced insulin secretion." (PMID 33102766, 2020). "The linear model which best fitted to our data was that using fibrosis stage as dependent dichotomic variable (F0–F2 vs F3–F4), and fasting glucose; fasting insulin; HOMA index; creatinine; eGFR; total, HDL, and LDL cholesterol; triglycerides, and BMI as independent values." (PMID 32782961, 2020).
fibrosis (continued). "Secondly, we evaluated whether the miRNAs differentially expressed in insulin resistant HSCs could impact on NAFLD-related fibrosis by using an experimental model of IR-NASH." (PMID 31671785, 2019). "Also, the frequency of NK cells in adipose was unaltered by NAFLD disease activity, level of fibrosis, and insulin sensitivity." (PMID 31214196, 2019). "On the other hand, insulin secretion in the advanced fibrosis groups continued until 120 minutes." (PMID 24223115, 2013). "Elevated ALT is coincident with increased serum concentrations of alanine, proline, and other amino acids in the MASLD + fibrosis group, supporting the metabolic funneling of amino acids for use in gluconeogenesis, which may explain the reduced insulin sensitivity in this group." (PMID 37893503, 2023). "Regarding physical and biochemical factors, the frequently assessed waist-to-hip ratio and plasma glucose, insulin, GGT, and triglycerides were significant predictors of NAFLD-fibrosis, in keeping with previous data." (PMID 33429859, 2021). "Finally, astaxanthin prevented and reversed hepatic fibrosis to a greater extent than did vitamin E. Our in vitro study demonstrated that astaxanthin can act directly on hepatocytes by decreasing lipid accumulation, enhancing insulin signaling and suppressing inflammatory signaling." (PMID 27347998, 2016). "Pharmacological inhibition of HCV improves peripheral (but not hepatic) insulin sensitivity in non-diabetic, lean individuals with chronic hepatitis C without significant fibrosis." (PMID 31170218, 2019). "Individuals with NAFLD fibrosis had significantly higher serum levels of aspartate aminotransferase (AST), alanine aminotransferase (ALT), insulin, and triglycerides compared to individuals without fibrosis." (PMID 30005700, 2018). "Insulin also seems to increase the expression of some fibrogenic signaling molecules, but the role of hyperglycemia and hyperinsulinemia in activating HSCs in the context of NAFLD-associated fibrosis is still not elucidated." (PMID 38398781, 2024). "However, age, HbA1c, insulin, and HOMA-IR were no longer associated with liver steatosis and fibrosis in the multivariate analysis." (PMID 39698035, 2024). "Moreover, addition of trans fats or high levels of fat to a fructose diet promoted glucose and insulin insensitivity and fatty liver formation without fibrosis." (PMID 27347998, 2016).